CXCR1 (C-X-C motif chemokine receptor 1)
Diseases named in the same sentence as CXCR1 in open-access papers (continued):
Sharing a sentence is not in itself a finding about the gene and the disease.
liver disease (1 paper, 2011). "The enhanced monocytic CXCR1 expression could likely result from induction by Th2-cytokines, because IL-4 was found increase with progression of liver disease (not shown) and to correlate with serum IL-8 in our cohort." (PMID 21731723, 2011).
Lupus (1 paper, 2022). "In particular, Cluster #42 for cv-score of 0.7 is a subpopulation of mature neutrophils (defined as CD66ace+CD66b+) whose levels of expression for CXCR1, CD15, CXCR2, IgA, CD66ace, CD66b, CD10, CD45RO, CD24 and CD16 best distinguishes between Lupus patients and Healthy donors." (PMID 36191000, 2022).
MALT lymphoma (1 paper, 2015). An indolent, extranodal type of non-Hodgkin lymphoma composed of small B-lymphocytes (centrocyte-like cells). "In comparing gastric to extragastric MALT lymphomas, the upregulation of CXCR1 and CXCR2 accompanied by downregulation of CCR8 and CX3CR1 and loss of XCR1 expression in extragastric MALT lymphomas appear to be key determinants for the site of origin of MALT lymphomagenesis." (PMID 25922601, 2015).
myocardial ischemia (1 paper, 2022). A disorder of cardiac function caused by insufficient blood flow to the muscle tissue of the heart. "On one hand, interleukin-8 (IL-8) secreted after myocardial ischemia recruits bone marrow-derived mesenchymal stromal cells (MSCs) to the sites of degenerated tissue of myocardium by interacting with CXCR1 overexpressed on MSCs, thereby reducing the ischemic area and improving cardiac function." (PMID 36325326, 2022). "Although we have revealed and proved that GXNI can play an anti-acute myocardial ischemia-reperfusion injury via inhibiting the CXCR1-NF-κB-COX-2/ICAM-1/VCAM-1-mediated IL-8 signaling pathway, there are still some issues that need to be addressed by further investigation." (PMID 36325326, 2022).
neuroendocrine tumor (1 paper, 2024). "CXCR2 is overexpressed predominantly in neuroendocrine tumor (NE) cells, which produce CXCL8; whereas, CXCR1 expression appears to be restricted to non-NE tumor cells." (PMID 39766038, 2024).
ovarian adenocarcinoma (1 paper, 2020). An adenocarcinoma that arises from the ovary. "Finally, we evaluated the levels of the three CXCR1/2 ligands in serum from patients with ovarian adenocarcinoma collected at diagnosis." (PMID 31504643, 2020).
papillary thyroid carcinoma (1 paper, 2021). "It is well established that the CXCL5/CXCR2 and IL-8/CXCR1/CXCR2 axes contribute to carcinogenesis by promoting tumor cell proliferation, migration, and invasion, and the EMT process of many tumor cells, including NSCLC, hepatocarcinoma cells, and papillary thyroid carcinoma cells." (PMID 34822613, 2021).
pleural tumor (1 paper, 2018). "Our experiments using CXCR1- and CXCR2-deficient mice support that pleural tumor cell-secreted CXCL1/PPBP is cardinal for MPE and are in line with a previous study demonstrating increased production of CXCL1 by tumor cells during human MPE development that mobilizes regulatory T cells." (PMID 29445180, 2018).
pneumococcal infection (1 paper, 2017). Infections with bacteria of the species streptococcus pneumoniae. "Altogether, the current results show that the chemokine receptors CXCR1/2 have a major role in driving pulmonary inflammation and damage in the context of severe IAV and pneumococcal infections." (PMID 29326698, 2017). "Modulation of the inflammatory response by blocking CXCR1/2 improves disease outcome during respiratory influenza and pneumococcal infections, without compromising the ability of the murine host to deal with infection." (PMID 29326698, 2017). "Inhibition of CXCR1/2 prevented this exacerbated response, even after sequential IAV and pneumococcal infection without compromising adaptive responses against the virus." (PMID 29326698, 2017).
pneumococcal pneumonia (1 paper, 2017). A febrile disease caused by STREPTOCOCCUS PNEUMONIAE. "Due to the presence of neutrophilic inflammation in the course of bacterial lung infection with S. pneumoniae, we wondered whether treatment with the CXCR1/2 antagonist would affect pneumococcal pneumonia." (PMID 29326698, 2017).
prostate (1 paper, 2024). "A third factor that could account for the differential effect of CXCR1 versus CXCR2 expression in prostate tumorigenesis could be the expression of chemokines in the tumor microenvironment (TME)." (PMID 39766038, 2024). "Since CXCR2 expression was shown to promote PCa growth the data likely indicate that CXCR1 and CXCR2 play opposing roles in prostate tumorigenesis." (PMID 39766038, 2024). "In contrast to CXCR2, CXCR1 expression inhibited PSA expression suggesting that the two receptors may couple to distinct pathways to modulate prostate tumorigenesis." (PMID 39766038, 2024).
Pruritus (1 paper, 2025). Pruritus is an itch or a sensation that makes a person want to scratch. "Similarly, a positive correlation with pruritus NRS was observed for IL4R, CXCR1, TGFB1, IL13RA2." (PMID 41268562, 2025).
pulmonary arterial hypertension (1 paper, 2025). Pulmonary arterial hypertension (PAH) is a group of diseases characterized by mean pulmonary artery pressure >20 mmHg and elevated pulmonary arterial resistance leading to right heart failure. "CXCL8 (IL-8) and its receptors CXCR1 and CXCR2 are upregulated in pulmonary arterial hypertension, with CXCL8 promoting the recruitment and activation of inflammatory cells through binding to CXCR1/2, exacerbating pulmonary artery inflammation and remodeling." (PMID 40385572, 2025).
relapsing-remitting multiple sclerosis (1 paper, 2013). The most common clinical variant of multiple sclerosis, characterized by recurrent acute exacerbations of neurologic dysfunction followed by partial or complete recovery. "Patients with relapsing-remitting multiple sclerosis (RRMS) have an increased number of neutrophils that regulated phenotypic changes such as reduction of apoptosis and higher expression of TLR2, FPR1, CXCR1, and CD43." (PMID 24174969, 2013).
retinoblastoma (1 paper, 2025). A malignant tumor that originates in the nuclear layer of the retina. "Moreover, in the high-ICI subgroup, CD83, HLA-DOA, IRF4, DOK3, and CXCR1 genes were also hypermethylated and thus associated with the presence of retinoblastoma." (PMID 41150792, 2025).
rhabdomyosarcoma (1 paper, 2022). A rare aggressive malignant mesenchymal neoplasm arising from skeletal muscle. "The efficacy of anti-PD-1 treatment was improved by genetic deficiency or inhibition of CXCR1/2 in murine models of oral and lung carcinomas, rhabdomyosarcomas, pancreatic adenocarcinoma, and prostate cancer." (PMID 35158948, 2022).
sarcopenia (1 paper, 2025). Progressive decline in muscle mass due to aging which results in decreased functional capacity of muscles. "Univariate logistic regression showed that higher CXCR2 and CXCR1 expression increased sarcopenia risk, while lower LPL and IL18 expression was protective." (PMID 40625358, 2025). "In conclusion, the interplay between NETosis, along with its associated chemokine receptors CXCR1 and CXCR2, and sarcopenia encompasses intricate interactions among inflammatory pathways, cellular migration, and tissue remodeling." (PMID 40625358, 2025). "The research pinpointed three genes associated with chemokines and NETosis (CXCR1, CXCR2, LPL) and developed highly accurate diagnostic models, offering a new and preliminary approach to differentiate sarcopenia and its early stages." (PMID 40625358, 2025). "The genes identified in this study, namely CXCR1, CXCR2, and LPL, exhibit substantial potential as clinical diagnostic and therapeutic targets for sarcopenia." (PMID 40625358, 2025). "By employing integrative bioinformatics strategies and multiple machine learning algorithms, we have successfully identified three signature chemokine- and NETosis-associated genes (CXCR1, CXCR2, and LPL) and constructed robust diagnostic models for sarcopenia detection." (PMID 40625358, 2025). "Our research found that CXCR1 and CXCR2 were notably higher in the sarcopenia group, with single-gene GSEA and GSVA confirming their strong association with increased JAK-STAT pathway activity." (PMID 40625358, 2025). "Subsequently, an intersection of these three primary gene sets, as determined by univariate logistic regression, LASSO, and SVM-RFE models, led to the identification of three optimal signature genes—CXCR2, CXCR1, and LPL—for sarcopenia." (PMID 40625358, 2025). "CXCR1 and CXCR2 levels were significantly higher, and LPL levels were lower in the sarcopenia group, consistent with the training group." (PMID 40625358, 2025). "To explore the roles of CXCR2, CXCR1, and LPL in sarcopenia-related pathways, we analyzed these genes individually using single-gene GSEA and GSVA." (PMID 40625358, 2025). "High CXCR1 and CXCR2 and low LPL levels may indicate sarcopenia progression, aiding early detection." (PMID 40625358, 2025). "Exploring CXCR1 and CXCR2 expression on muscle cells and their role in muscle inflammation could clarify mechanisms behind sarcopenia." (PMID 40625358, 2025).
small cell carcinoma (1 paper, 2015). A neuroendocrine carcinoma composed of small malignant cells which are often said to resemble "oat cells" under the microscope. "This study focused on the impact of CXCR1 and CXCR2 antagonism by G31P on proliferation, migration, survival and growth of non-small cell carcinoma cells and tumors in vitro and in vivo, the latter as determined in a xenograft mouse model." (PMID 26087179, 2015).
streptococcal infection (1 paper, 2022). Any of the several infectious disorders caused by members of streptococcus, a genus of gram positive bacteria belonging to the family Streptococcaceae. "Potential SpyCEP antagonists modelled on CXCL8 but with reduced CXCR1 and CXCR2 activity have previously been described and could in theory provide adjuvant therapies for more severe invasive streptococcal infections that fail to respond to antibacterial agents alone." (PMID 34649250, 2022).
tongue cancer (1 paper, 2014). A malignant neoplasm affecting the tongue. "The two ligands for CXCR1, CXCL6 and CXCL8, which also activate CXCR2, are both up-regulated, indicating that a shift towards activation of CXCR2 could be of importance for tongue carcinoma." (PMID 24395654, 2014).
ureterocele (1 paper, 2007). A cystic and dysplastic dilation of the distal ureter within the bladder that may extend into the bladder neck and urethra. "The relative contribution to APN susceptibility of vesico-ureteric reflux (VUR) and CXCR1 sequence variation was therefore examined in the APN prone children, where 11/24 had VUR and two had structural abnormalities (ureterocele and double ureters)." (PMID 17786197, 2007).
visceral leishmaniasis (1 paper, 2011). A severe form of leishmaniasis characterized by irregular bouts of fever, substantial weight loss, swelling of the spleen and liver, and anemia (which may be serious). "Here we investigate the role of CXCR1/CXCR2 in visceral leishmaniasis (VL) in India." (PMID 22171941, 2011).
tumor (476 papers, 2008 to 2026). "In this context, HBV-associated tumor cells release high amounts of interleukin 8 (IL-8), which binds to endothelial CXCR1, leading to increased LSEC permeability to facilitate tumor invasion." (PMID 40595432, 2025). "Heightened levels of CXCL8 along with overexpression of CXCR1 or CXCR2 have been implicated in promoting tumor cell proliferation and metastasis through the activation of PI3K/AKT and ERK1/2 MAPK signaling pathways." (PMID 40124384, 2025). "Immune microenvironment analysis revealed that blocking the CXCL8/CXCR1/2 pathway reduced the infiltration of MDSCs and tumor-associated neutrophils while enhancing the infiltration and activity of CD8+ T cells." (PMID 40573881, 2025). "linked CD70 to immunosuppression and augmented anti-tumor responses by engineering IL-8 receptor (CXCR1/CXCR2)-modified anti-CD70 CAR-T, leveraging radiation-induced IL-8 release to enhance tumor trafficking." (PMID 40896423, 2025). "Modulation of IL-8 by CXCR1/2 chemokine receptors promotes various intracellular signaling cascades that lead to tumor-associated inflammation." (PMID 40176809, 2025). "The IL-8/CXCR1/2 axis promotes the accumulation of tumor-associated neutrophils, macrophages, and myeloid-derived suppressor cells (MDSCs) within the tumor microenvironment (TME), thereby amplifying immunosuppression." (PMID 41394847, 2025). "In a study of NSCLC patients with metastatic disease, a high expression of CXCR1 was associated with a poor prognosis reflected by the patient’s tumor node metastasis (TNM) stage." (PMID 39114657, 2024). "The diagnostic sensitivity of CXCL1 and CXCR1 was higher than that of the classical tumor marker and increased in the combined analysis with CEA." (PMID 37509572, 2023). "Firstly, CXCL2 (one ligand of CXCR1/2) was associated with tumor-associated neutrophil recruitment in the KIRC and CM datasets." (PMID 37540227, 2023). "The CXCR1/CXCR2 signaling nexus directly influences the sensitivity of tumor cells to chemotherapies by altering pathways associated with apoptosis and multidrug resistance, resulting in a poor prognosis in human cancer studies." (PMID 37270599, 2023). "Previous studies have shown that tumor-associated macrophages (TAMs) widely express CXCR1/2 and be recruited to the tumor bed through the CXCL8-CXCR1/2 axis facilitating immune escape." (PMID 35550147, 2022). "It has been reported that the activation of the CXCR1/CXCR2 or CXCR4/CXCR7 pathways is associated with tumor aggressiveness and poor prognosis." (PMID 34233297, 2021). "Kaplan–Meier analysis confirmed that PTENLOW and CXCR1/2HIGH tumours were associated with a significantly reduced time to BCR (P < 0.001; HR 2.65) and importantly with the development of metastasis (P = 0.002; HR 3.51) after RT treatment." (PMID 32743555, 2020). "Chemokine receptors CXCR1, 2, 3, 4, and 7 have been implicated in tumor angiogenesis, sustaining tumor growth and expansion both in zebrafish and humans." (PMID 32161595, 2020). "In TCGA dataset, the expression of CXCR3/5/6 in ccRCC was positively correlated with the grade of malignancy or tumor stage, and the expression levels of CXCR1/2 were negatively associated with pathological grade." (PMID 33324682, 2020). "Molecular-mediated and pharmacological-based inhibition of CXCR1/CXCR2 signalling sensitized each of the three PTEN-deficient tumour models to clinically relevant doses of IR." (PMID 32743555, 2020). "To harness tumor-derived IL-8 for therapeutic benefit, we have co-expressed either of its cognate receptors (CXCR1 or CXCR2) in CAR T-cells that target the tumor-associated αvβ6 integrin." (PMID 31091832, 2019). "The pro-inflammatory CXC cytokine interleukin 8 (IL-8), secreted by tumour cells and tumour-associated macrophages (TAMs), are critical factors that bind to the receptors CXCR1 and CXCR2 to promote tumour angiogenesis and metastasis." (PMID 29487724, 2018).
tumor (continued). "Our observation was that CXCR1 was uniformly expressed in tumor-associated microvessels in GBM while CXCR2 expression was limited to tumor cells." (PMID 30086759, 2018). "CXCR1/2 and their ligands have been implicated in angiogenesis, tumor dissemination, myeloid cell recruitment, and self‐seeding of primary tumors, but their potential impact in metastatic organ tropism is less well defined." (PMID 28341702, 2017). "In summary, our current model is that TNBC cells secrete IL-8 which interacts with the CXCR1/2 receptor on tumor associated fibroblasts and macrophages in the tumor microenvironment." (PMID 28947965, 2017). "The IL-8 secreted by these tumor associated fibroblasts and macrophages interacts with the CXCR1/2 receptor on TNBC cells enhancing TNBC tumor growth and metastatic extravasation and colonization." (PMID 28947965, 2017). "We also found that mRNA encoding IL-8 mRNA, the ligand of CXCR1, was expressed by the tumor cells, and that these cells were partly stained with antibody to IL-8." (PMID 25123545, 2014). "Therefore, targeting CXCR1/2 should alter the accumulation of tumor-associated myeloid cells and MDSCs in the TME, favoring a less immune-suppressive TME." (PMID 40904502, 2025). "The CXCR1/2 receptors have approximately 76% sequence homology and play a pivotal role in the initiation and spread of inflammatory processes and are associated with tumor growth and metastasis by binding to their ligand CXCL830." (PMID 39962077, 2025). "Given that IL-8 has been implicated in tumor resistance to a broad number of cancer therapies, we evaluated whether blockade of IL-8 signaling via inhibition of the CXCR1/2 receptors may improve the response of HPV-negative HNSCC to various chemotherapies." (PMID 39639338, 2024). "However, it is known that CXCR1 is associated with a direct migration of neutrophils and neutrophil infiltration in several cancers and is implicated in both anti- and pro-tumor roles." (PMID 38067341, 2023). "Our study is the first to evaluate the diagnostic significance of serum CXCL1 and CXCR1 levels in CRC patients in comparison to well-established tumor markers, such as the carcinoembryonic antigen (CEA), and markers of inflammation, such as C-reactive protein (CRP)." (PMID 37509572, 2023). "CXCR1 and 2 are expressed in cancer cells, endothelial cells, infiltrating neutrophils, and tumor-associated macrophages, suggesting their important regulatory roles within the tumor microenvironment." (PMID 26414070, 2015). "RT-PCR showed expression in the tumor of mRNA encoding IL-8, the ligand of CXCR1." (PMID 25123545, 2014). "Additionally, tumor cells harboring oncogenic mutations or loss of tumor suppressor genes that lead to the activation of specific signaling pathways have been shown to regulate CXCL8 or CXCR1/2 expression." (PMID 24276377, 2013). "Finally, reprogramming of immunosuppressive myeloid cells (e.g., CSF1R or PI3K-γ inhibitors) can deplete or repolarize tumor-associated macrophages, while blockade of chemokine receptors such as CXCR1/2 or CCR2 reduces the recruitment of myeloid-derived suppressor cells." (PMID 40941014, 2025). "Thus, CXCR1/2 not only regulates neutrophil trafficking from the bone marrow to peripheral circulation or inflammation sites but also plays a role in tumor progression by facilitating the migration of tumor-associated myeloid cells into the TME." (PMID 40904502, 2025). "To understand how pathway activity differs among tumor-associated neutrophil subsets, we analyzed the pathway variance and found significant downregulation of pathways that positively regulate immune cell functions, such as T cell proliferation, migration, and activation in CXCR1+ neutrophils." (PMID 39638994, 2024).